APP (amyloid beta precursor protein)
Diseases named in the same sentence as APP in open-access papers (continued):
Sharing a sentence is not in itself a finding about the gene and the disease.
dementia (continued). "Conversely, a small cohort of patients who inherited an extra copy of APP due to microduplication of small portions of chromosome 21q containing the APP locus developed AD-like dementia with plaque deposition." (PMID 21871088, 2011). "The clinical characteristics in patient with APP-duplications are typically early-onset dementia, cerebral amyloid angiopathy (CAA) and intracerebral hemorrhage (ICH)." (PMID 22044463, 2011). "Accumulating evidences also support the notion that increasing APP protein levels directly results in Aβ over-production, and that APP overexpression alone is sufficient to induce neurodegeneration an dementia." (PMID 21982160, 2011). "Mutated forms of both amyloid precursor protein (APP) and presenilin 1 (PS1) lead to an increased rate of amyloid deposition and therefore an earlier onset of the dementia associated with AD." (PMID 15689237, 2005). "Contrary to the prolonged silent phase of asymptomatic amyloidosis, standard APP transgenic overexpression models with high levels of APP and Aβ expression develop early synaptic dysfunction and dementia-like deficits before the onset of Aβ pathology, a disease stage never observed in humans." (PMID 41292846, 2025). "Examining the mutant PSEN2 (N141I (Volga) and M239V) and APP (V717G, V717L, V717I, V717F and A713T) cohorts shows that a large proportion of carriers presented with dementia later than expected for PSEN2, and earlier than expected for APP, based on biochemical AAOs." (PMID 40281586, 2025). "AD is the leading cause of dementia with 95% of all AD cases arising as late-onset sporadic cases (LOAD), with only 5% being linked to disease-causing genes that include apolipoprotein E (ApoE4), presenilin (PSEN), and amyloid precursor protein (APP)." (PMID 40558500, 2025). "Therefore, VIP maintained the intrinsic inhibitory activity of GSK3β and BACE1 and exerted a synergistic anti-dementia therapeutic effect, which was consistent with the improvement in behavioral tests observed in APP/PS1 mice treated with VIP@siScr." (PMID 38734698, 2024). "Additionally, APP haploinsufficiency prevented memory deficits in familial British dementia mouse models, and PTEN-induced putative kinase 1 (PINK1) was associated with memory impairment induced by APP." (PMID 38396891, 2024). "First, several major YOD risk factors, such as APOE ε4 alleles; APP, PSEN1, and PSEN2 genes; family history of dementia; history of traumatic brain injury; hearing loss; and education level could not be obtained." (PMID 38926887, 2024). "The increased expression of not only APP, but also others of the more than 310 genes on chromosome 21 may contribute to and likely modulate AD-like dementia pathology in the diverse DS phenotypes." (PMID 38554150, 2024). "These considerations suggest that early diagnosis of SAD, even before the onset of dementia, may be possible if APP gencDNA in nucleic acids released into plasma in response to neuronal damage can be detected." (PMID 38066066, 2023). "This suggests that one or several duplicated genes in DS may provide partial protection against the pro-hemorrhagic effects of APP duplication similarly to BACE2 involvement in age at onset of dementia in DS." (PMID 37170141, 2023). "For instance, the D678N mutation on APP has been reported to cause AD-related dementia without a significant change in Aβ production which suggests the impairment of other APP-associated processes." (PMID 37387352, 2023). "More importantly, the Aβ amount in mice hippocampi, cortexes and femurs were markedly decreased after treatment with HLE, proving that hops could alleviate senior osteoporosis and dementia in APP/PS1 mice through removing Aβ deposition." (PMID 36677642, 2023). "AD-associated succinylation of APP occurred at a critical site (K612) in nine of ten brains from AD patients but not in brains from age-matched subjects with no dementia, and the following experiments demonstrated it to be pathologically important." (PMID 35013160, 2022).
dementia (continued). "Increases in glucocorticoid levels have been found to relate to the degree of dementia in elderly people and AD patients; glucocorticoid exposure can trigger incorrect processing of amyloid precursor protein (APP) and reduce the Aβ clearance rate, thereby inducing cognitive dysfunction." (PMID 35663199, 2022). "We found through experiment in vivo that QZZD could protect the neurons, reduce damage to neural function, and enhance spatial learning and memory function in APP/PS1 double transgenic mice with dementia." (PMID 36340795, 2022). "No additional variants were detected in PSEN2, APP, or other dementia causative genes (e.g., MAPT, GRN, and TARDBP)." (PMID 35932032, 2022). "In conclusion, QZZD could significantly improve spatial learning and memory in APP/PS1 double transgenic mouse with dementia." (PMID 36340795, 2022). "Not only the APP gene is responsible for dementia in DS, GATD3A, SOD1, ERG, BACE2, DSCR1/RCAN1, APOE (19q13.32), BACE1 (11q23.3), IL1B (2q14.1), GSAP (7q11.23), UBB (17p11.2), and IRS1 (2q36.3) genes may also play a major role in dementia in DS." (PMID 35676933, 2022). "Concerning APP duplications carriers, apart from dementia, they may present with seizures and other focal cortical symptoms such as aphasia, apraxia and dyscalculia, extrapyramidal, pyramidal or behavioral symptoms." (PMID 34830236, 2021). "The exact mechanisms of APP contributing to the development of dementia are unknown by far, but cleavage of APP by secretases leading to the formation of a smaller peptide, Aβ, is considered a crucial step." (PMID 32331528, 2020). "APP and its peptides are often studied in TBI rodent models that carry the mutated PSEN transgenes in an effort to show direct relationships to early onset dementia." (PMID 33071724, 2020). "The Dementia Mutation Database indicates that approximately 300 mutations in presenilin-1 (PS1) and presenilin-2 (PS2) and 635 mutations in amyloid precursor protein (APP) constitute causative factors for EOAD development." (PMID 32204380, 2020). "A dementia-CVD continuum hypothesis is further demonstrated through the vascular involvement of dementia-prone transgenic APP mice." (PMID 32130931, 2020). "In this study, we used the APP/PS1 transgenic mouse model as it has been used previously to evaluate the process of amyloidogenesis at the pre-dementia phase of AD through the accumulation of Aβ deposits and plaques in the Tg mouse brain tissues and the retina." (PMID 32719582, 2020). "The finding that the A673T APP mutation protects against late-onset AD and non-AD dementia, is notable for several reasons." (PMID 32022689, 2020). "As platelet-derived APP is also processed via identical amyloidogenic and non-amyloidogenic pathways as brain APP, they are likely to be associated with pathologic changes in dementia." (PMID 32485903, 2020). "First, it links APP processing to the sporadic forms of dementia." (PMID 32022689, 2020). "Moreover, APP gene is located at chromosome 21, and Down syndrome patients have an extra copy of this chromosome, thus leading to the development of early onset dementia with AD characteristics." (PMID 31722748, 2019). "This genetic link between APP processing and dementia has provided some of the foundation for the “amyloid hypothesis,” which indicts Aβ as the main pathogenic factor responsible for neurodegeneration." (PMID 31496118, 2019). "Moreover, the dementia of patients with APP duplication show a virtually complete penetrance by the age of 65." (PMID 29599933, 2018). "The abnormal processing of amyloid precursor protein (APP) causes accumulation of insoluble Aβ, which induces free-radical reactions and inflammation and finally leads to the death of neurons and development of dementia." (PMID 29533975, 2018).
dementia (continued). "This hypothesis was further reinforced by the identification of a protective amyloid precursor protein (APP) mutation near the protein’s beta-cleavage site, which protects against the development of late onset dementia." (PMID 29467644, 2018). "None of these patients had a family history of stroke or dementia, and none had any pathogenic mutation in the APP, PSEN1 and PSEN2 genes to explain early Aβ pathology." (PMID 29450646, 2018). "In this regard, it will be worth testing whether the TauDN allele in heterozygosis prevents memory and synaptic deficits in KI mouse models of human dementias characterized by increased APP processing and tauopathy." (PMID 28786980, 2017). "Given the frequency of variants identified in MAPT, GRN and C9ORF72, but also in our previous analysis of PSEN1, PSEN2 and APP, in the Turkish cohort of dementia patients studied, a standardized molecular screening procedure for these genes should be implemented in Turkey." (PMID 27632209, 2016). "In addition, the link between Down syndrome (DS) and AD regarding neuropathogenesis and dementia, supports the relevance of Aβ even further, because DS patients have three copies of chromosome 21 and APP is located at the same chromosome." (PMID 26388726, 2015). "•We have used exome sequencing to investigate rare coding variability in Mendelian dementia genes (APP, PSEN1, PSEN2, GRN, MAPT, and PRNP) in a cohort composed of 141 late-onset sporadic Alzheimer's disease cases and 179 elderly controls, autopsy proven from the UK." (PMID 25104557, 2014). "To investigate this intriguing hypothesis, we analyzed rare coding variability in 6 Mendelian dementia genes (APP, PSEN1, PSEN2, GRN, MAPT, and PRNP), in 141 LOAD patients and 179 elderly controls, neuropathologically proven, from the UK." (PMID 25104557, 2014). "Dementia in DS can provide an important model to study the role of APP and related genes in AD." (PMID 24462566, 2014). "In addition to APP, mutations in genes that regulate APP processing, such as PSENs and BRI2/ITM2B, cause dementias." (PMID 25247712, 2014). "While β- and γ-secretases cooperatively convert APP into Aβ, α-secretase is a competing pathway for APP which diverts the substrate APP into production of sAPPα, which is non toxic and effectively prevents the formation of amyloid plaques and AD-related dementia." (PMID 22700373, 2012). "Interestingly, clinical phenotypes in Flemish APP carriers overlapped to the extent that cerebral haemorrhages were reported in offspring of patients having dementia while patients with strokes had offspring developing progressive dementia." (PMID 19468344, 2009). "The regulation of APP processing to Aβ is inherently complex; nonetheless, the discovery that these LDL receptor family members are able to affect its processing is an important step to uncovering new therapies to reduce Aβ and its associated dementia." (PMID 16930455, 2006). "Finally, Cluster 3 appears to be a lower risk group for the development of dementia due to AD, defined mainly by rare (perhaps protective) variants in APP and almost no APOE ε4 individuals." (PMID 38693203, 2024). "At least two cases have been reported on persons born with a trisomy of only part of chr21 that did not include APP, with DS but lacking Aβ pathology in their brains and did not develop dementia suggesting it is the trisomy of APP that confers the high risk for AD in the DS population." (PMID 38102482, 2024). "However, as far as we know, these studies did not carry out a genetic screening on AD patients to verify the presence of mutations in the PS1, PS2 and APP genes or have included patients with no family history of dementia." (PMID 36834612, 2023). "Trisomy 21 results in APP overexpression; however, others studies support that trisomy 21-related dementia may be caused by overexpression of non-APP genes leading to a decrease in the soluble amyloid-beta-38, and amyloid-beta-40." (PMID 32355332, 2021).
dementia (continued). "Furthermore, studies have suggested that the genetic recombination in the APP gene may be a key event in the pathogenesis of sporadic AD, which is a type of dementia." (PMID 34374199, 2021). "AD is a progressive neurodegenerative pathology leading to dementia characterized by the accumulation in AD-affected brains of hyperphosphorylated Tau (pTau) protein and of toxic amyloid beta (Aβ) peptide, a product of amyloid precursor protein (APP) processing." (PMID 33079262, 2021). "Therefore, changes in intracellular transport that are related to changes in APP processing may lead to neuronal iron level increases and oxidative stress in dementia pathology." (PMID 34707492, 2021). "Also, molecular and genetic research should be conducted to clarify the role of APP in the processes of neurodevelopmental alteration and to understand if processes leading to neurodegeneration in mental disease are different from those observed in dementia." (PMID 34679416, 2021). "The aim of the present study was to determine whether MSL prevented early progression of dementia in AD-related amyloid precursor protein (APP)/presenilin 1 (PS1) double transgenic mice, and to explore the potential mechanisms of action involved in neuronal protection." (PMID 29636677, 2018). "The cause of this is apparently an extra copy of APP (amyloid precursor protein gene located on chromosome 21), as one individual with DS at age 74 (with no dementia, and no amyloid pathology in the brain) has been described who was born with partial chromosome 21 trisomy that did not include APP." (PMID 26648852, 2015). "Thus, studying the function of pre-synaptic APP and β-CTF may help clarifying not only the biochemical mechanisms by which APP exerts its function in synaptic plasticity and memory, but also the molecular mechanisms that lead to dementia." (PMID 25247712, 2014). "Thus, we screened 6 Mendelian dementia genes (APP, PSEN1, PSEN2, MAPT, GRN, and PRNP) aiming to establish whether rare coding variability in these genes is responsible for an appreciable portion of the LOAD risk." (PMID 25104557, 2014). "Further study of the age-related effects of expression of the H63D variant on APP metabolism in an in vivo model should further define the interrelationships of HFE, APP, iron, and cholesterol metabolism, and the mechanisms by which they may contribute to dementia." (PMID 25071582, 2014). "Given the evidence that increased APP processing by Bace1 leads to human dementia and that β-CTF can have a pathogenic role, it will be important to understand whether full-length APP and β-CTF can differentially regulate pre-synaptic vesicles exocytosis, endocytosis and recycling." (PMID 25247712, 2014). "APP but not PRNP duplication is a significant cause of early onset dementia in the UK." (PMID 21193246, 2012). "In APP/PS1 transgenic mice, a dementia model, APS improved cognitive behavior and reduced the effects of metabolic stress but did not reduce β-amyloid accumulation." (PMID 41154559, 2025). "One protein that binds to C99 and full-length APP via Aβ-Nt is integral membrane protein 2B (ITM2b/BRI2), the gene responsible for familial British and Danish dementia (FBD and FDD, respectively)." (PMID 36766796, 2023). "In familial forms of early-onset AD (FAD) caused by mutations in the amyloid precursor protein (APP) or presenilin (PS) 1 and PS2, the deposition of Aβ peptides in amyloid plaques is hypothesized to trigger a pathological cascade that ultimately leads to NFT pathology and clinical dementia." (PMID 35883442, 2022). "BDNF expression is decreased in hippocampal and cortical neurons from 21-month APP/BIN1/COPS5 3xTg-AD mice, and is strongly reduced in buffy coat samples from patients with dementia or PD than in healthy control subjects." (PMID 35269588, 2022). "Amyloid precursor protein (APP) undergoes sequential cleavages by β-secretase and γ-secretase and gives rise to β-amyloid (Aβ), responsible for dementia." (PMID 36611925, 2022).
dementia (continued). "Clinical-genetic studies demonstrate that the Hsa21 gene amyloid precursor protein (APP) is central to early AD onset in people with DS5,6, but other genes, including some found on Hsa21, modulate age of dementia onset." (PMID 33707583, 2021). "In this perspective, we review evidence for APP SGR in AD pathogenesis and discuss its possible relevance to other AD-related dementias." (PMID 32457796, 2020). "Consistent with our findings in APP/PS1 mice, however, recent studies in patients with dementia (diagnosed as mild to moderate AD in Refs." (PMID 32857763, 2020). "Aged C57BL/6 mice and amyloid precursor protein (APP) mice display behavioral disturbances that mimic behavioral and psychological symptoms of dementia (BPSD)." (PMID 32457634, 2020). "Further report demonstrates that Cur improves bone microarchitecture and enhances mineral density in amyloid precursor protein (APP)/presenilin (PS1) transgenic mice, a transgenic mouse representing the pathological changes of senile dementia and osteoporosis." (PMID 32612986, 2020). "Given the very rare frequency of APP, PSEN1, and PSEN2 pathogenic mutations detected in the screened patients (two individuals with EOAD), our hypothesis should encourage genetic screening in larger cohorts of both EOAD and LOAD, as well as dementia cases using the gene panel." (PMID 30917570, 2019). "On the contrary, miRNA-195-5p, elevated in AD and sCJD, downregulates Aβ production by targeting APP and BACE1, and protects against chronic brain hypoperfusion-mediated dementia." (PMID 29357384, 2018). "Bace1 cleavage of APP is activated by synaptic activity and generates the β-CTF APP metabolite that exerts a pathological role in mouse models of dementia." (PMID 25247712, 2014). "Amyloid precursor protein (APP) experiences sequential cleavages by β-secretase and γ-secretase and gives rise to the dementia culprit β amyloid (Aβ) that is thought to initiate soluble oligomers, insoluble fibrils, and accumulated plagues." (PMID 25136630, 2014). "Since most of the identified proteins are not present in both diseases, we performed two independent PPI analyses: the first using the proteins associated with HF (NPPB, REN, ADIPOQ, VWF, ACE, IL6, and CRP) and the second using the proteins involved in dementia (CRP, APP, MAPT, APOE, ACE, and IL6)." (PMID 40699836, 2025). "Previous investigations have revealed that 3-MA can downregulate the expression of α-synuclein, amyloid precursor protein (APP), and phosphorylated Tau in the intestinal tissue of Parkinson’s disease dementia (PDD) mice, potentially alleviating PDD symptoms through the brain–gut axis pathway." (PMID 40430426, 2025). "Examination of the highlighted keywords revealed the commonality between HF and dementia, namely IL6, ACE, APOE, APP, ADIPOQ, LEP, and NPPB, suggesting that these proteins may link the two pathologies." (PMID 40699836, 2025). "Conversely, if the section carrying the APP gene is duplicated and not the rest of chr21, individuals (familial condition called DupAPP) do not show signs of DS but do develop dementia with 100% penetrance before the age of 60." (PMID 38102482, 2024). "Reduced HGF/MET signaling contributes to synaptic pathology in the 5 × FAD mouse model of AD; while FGF2 gene transfer restores hippocampal functions in APP/PS1 mice; CRH (corticotropin-releasing hormone) has been proposed to play important roles in AD and other dementias." (PMID 39234102, 2024). "APP, APOC1, APOE, SORL1, and MAPT are highly relevant common genes for AD and dementia." (PMID 38790243, 2024). "The sample size was small because of the rare occurrence of APP duplication and PSEN1 mutations and the additional specific inclusion criteria (e.g. known genetic mutation status and absence of dementia)." (PMID 39713236, 2024).